IRF7 (interferon regulatory factor 7)
Diseases named in the same sentence as IRF7 in open-access papers (continued):
Sharing a sentence is not in itself a finding about the gene and the disease.
schizophrenia (3 papers, 2023 to 2025). A major psychotic disorder characterized by abnormalities in the perception or expression of reality. "Six candidate genes (SFN, KDM5B, MYLK, IRF3, IRF7, and ID1) were identified with diagnostic significance for schizophrenia." (PMID 37113536, 2023). "IRF7 of the IRF family has also been proved to be related to schizophrenia." (PMID 37113536, 2023). "Furthermore, we established a schizophrenia diagnostic model based on genes associated with cellular senescence, which contain 6 candidate genes (SFN, KDM5B, MYLK, IRF3, IRF7, ID1)." (PMID 37113536, 2023).
type 2 diabetes (3 papers, 2015 to 2023). "Specifically, IRF7 and NLRC5 are associated with type 2 diabetes, and SP110 and ZBP1 are associated with waist circumference and body fat distribution, respectively." (PMID 25868721, 2015). "IRF7 transactivates MCP-1 by binding to its promoter in adipocytes, promoting the development of type 2 diabetes." (PMID 37638030, 2023).
ulcerative colitis (3 papers, 2023 to 2025). An inflammatory bowel disease involving the mucosal surface of the large intestine and rectum. "Ferroptosis is implicated in the progression of ulcerative colitis (UC), and interferon regulatory factor 7 (IRF7) contributes to cell death." (PMID 36336986, 2023).
autoimmune thyroid disease (2 papers, 2019 to 2021). Inflammatory disease of the thyroid gland due to autoimmune responses leading to lymphocytic infiltration of the gland. "The objective of this study was to investigate whether IRF7 polymorphisms are associated with autoimmune thyroid diseases (AITDs)." (PMID 30774658, 2019).
bladder cancer (2 papers, 2017 to 2024). "In bladder cancer cells, DAC treatment increased the double-stranded RNA sensors, MDA5, MAVS and RIG-1, intermediate mediator IRF7, and downstream targets IFI44 and IFI27 and IFN-γ by 2-fold to 70-fold compared to control cells." (PMID 29242529, 2017).
cognitive deficits (2 papers, 2020 to 2023). "Therefore, the upregulation of CCL2 by IRF7 and its associated molecules may reduce neurodegeneration in the CNS, reducing the cognitive deficits brought upon by HIV-Associated Neurocognitive Disorders (HANDs)." (PMID 36827648, 2023). "Interestingly, no alteration in spine density was detectable in any region of the hippocampus in Irf-7−/− mice upon infection, which is in line with the observation that a LGTV infection showed no cognitive impairment for this genotype." (PMID 32951602, 2020).
colon adenocarcinoma (2 papers, 2022 to 2023). "Moreover, IRF3 and IRF7 were linked to a poor prognosis in colon adenocarcinoma." (PMID 35012444, 2022). "To determine the relevance of our findings in human Colon adenocarcinoma, we assessed IFNγ/STAT1/IRF7/IFI35/CD8 expression with Timer database." (PMID 37380972, 2023).
cytomegalovirus infection (2 papers, 2021). A herpesvirus infection caused by Cytomegalovirus. "In this study we show that SMAD3, a TGFβ receptor-associated SMAD, cooperates with IRF7 to induce type I IFN during HCMV infection." (PMID 34411201, 2021). "In this study we show that SMAD3, a TGFβ receptor-associated SMAD, cooperates with IRF7 to induce type I IFNs during HCMV infection, highlighting a unique interconnection between TGFβ and IFN signaling." (PMID 34411201, 2021). "Also in a murine cytomegalovirus infection model, IRF7-deficient mice had a higher IFN-γ production during acute infection compared to wild-type mice." (PMID 34781942, 2021). "This study uncovers a novel link between SMAD3 and IRF7 in the induction of type I IFNs, highlighting the crosstalk between TGFβ and innate immune signaling during HCMV infection." (PMID 34411201, 2021). "In order to assess the role of miR-UL22A regulation of SMAD3 and IRF7-mediated signaling in the context of HCMV infection, we next tested the induction of IFN transcripts following infection with WT and ΔmiR-UL22A mutant viruses in tHF and ΔIRF7 cells." (PMID 34411201, 2021). "Together, these data support the hypothesis that SMAD3 and IRF7 cooperate to induce IFN production during HCMV infection, which has negative effects on viral replication." (PMID 34411201, 2021).
dementia (2 papers, 2022 to 2023). Loss of intellectual abilities interfering with an individual's social and occupational functions. "The expression of Irf7 may affect brain immune efficiency and is highly correlated with clinical dementia in patients with AD." (PMID 37895370, 2023). "Moreover, IRF7 expression in the human brain is highly correlated with AD clinical dementia, Braak score, and neuritic amyloid burden." (PMID 35526014, 2022).
dengue (2 papers, 2011 to 2018). "When we compared the acute samples with the samples collected at convalescence in our dengue positive patients we saw an up regulation of TLR7 and IRF7 which indicates an activation of the TLR7 signalling pathway." (PMID 21810247, 2011).
depression (2 papers, 2014 to 2021). "Among the genes that were upregulated were several that are key in inflammation including Interferon regulatory factor 7 (Irf7), a gene that is significantly downregulated in prefrontal cortex of patients with major depressive disorders." (PMID 25202975, 2014).
endotoxemia (2 papers, 2020 to 2023). "Prolonged production of IP-10 attracts CXCR3+ lymphocytes to lung tissues and triggers an exaggerated inflammatory response and lung injury during endotoxemia via the IFNβ–IRF7 axis." (PMID 37701855, 2023). "However, we found IRF7 could also be activated independently of the lipid overload in adipocytes and that it could be associated with MCP-1 production possibly through increased endotoxemia in obese individuals." (PMID 32437400, 2020).
eosinophilia (2 papers, 2020 to 2021). "In contrast, responses in high-risk BN rats were characterized by severe airways eosinophilia and exaggerated proinflammatory responses that failed to resolve, and complete absence of IRF7 gene networks." (PMID 34367159, 2021). "Anti-HMGB1 and anti-IL-33 treatment of IRF7-/- mice decreased ILC2 numbers in the lung, type-2 cytokine responses in BALF, and airway eosinophilia." (PMID 32658914, 2020).
gastric adenocarcinoma (2 papers, 2022 to 2024). "Interferon regulatory factor 7 (IRF7) was overexpressed in gastric adenocarcinoma, which was significantly correlated with poor OS and immune infiltration." (PMID 36189255, 2022).
gastric tumors (2 papers, 2019 to 2022). "IRF7, SIM1, IFNG, and HNF1A were predicted to be upstream regulators of the higher expressed genes in the EBV negative gastric tumors involved in cellular movement, inflammatory response, and immune cell trafficking." (PMID 31584998, 2019).
glomerulonephritis (2 papers, 2019 to 2025). A renal disorder characterized by damage in the glomeruli. "In mice, blocking IFN-I signaling reduces IRF7 and granzyme B expression in T cells, thus ameliorating glomerulonephritis." (PMID 40393992, 2025).
head and neck cancer (2 papers, 2023 to 2024). A primary or metastatic malignant neoplasm affecting the head and neck. "Research on head and neck cancer patients supports the idea that exercise may decrease inflammation, potentially linked to the downregulation of Irf7." (PMID 37895370, 2023). "In head and neck cancer, both IRF7 and IRF9 have been reported to be overexpressed." (PMID 39329063, 2024). "The present study demonstrated that IRF7 expression was negatively correlated with MORC3 in single head and neck cancer cells, which was correlated with the MORC3-mediated suppression of IRF7 expression." (PMID 39329063, 2024).
latent infection (2 papers, 2021). "In contrast, during Epstein Barr virus (EBV) latent infection, IRF7 expression is stimulated by latent membrane protein-1 (LMP-1) which in turn regulates expression of the EBNA1 Q promoter and LMP-1 itself." (PMID 34411201, 2021).
leukocytosis (2 papers, 2015 to 2025). "In PV, ON-GNPs targeting TLR9, IRF7, and IL-8 pathways may reduce thrombotic risk and leukocytosis, while in ET, they could mitigate platelet activation and chronic inflammation." (PMID 40016346, 2025). "Elevated IRF7 activity in HEL cells was associated with increased IL-8 secretion, a cytokine linked to thrombotic risk and leukocytosis in PV patients." (PMID 40016346, 2025).
Listeria infection (2 papers, 2012 to 2015). "IFN-β induction in IRF7-deficient macrophages was also strongly affected highlighting the important role of both transcription factors in response to Listeria infection." (PMID 22432012, 2012). "IRF1 could promote CD8+T cell maturity and induce a shift of the Th subset balance to a Th1 dominant state during Listeria infection, as well as activating expression of the cytokine Interferon beta like IRF7." (PMID 26465882, 2015).
lupus nephritis (2 papers, 2018 to 2025). Glomerulonephritis in the context of systemic lupus erythematosus. "These pathways are activated by key regulators such as IRF3, IRF7, and STAT1, which promote immune cell infiltration and contribute to organ damage, as seen in lupus nephritis inflammation." (PMID 39844998, 2025).
myocarditis (2 papers, 2018 to 2023). Myocarditis is a condition that is characterized by inflammation of the heart muscle (myocardium). "In our datasets, although the gene activity and RNA expression level of IRF3 showed minimal changes, the motif activity of IRF3 and IRF7 was decreased at myocarditis state across all cell subpopulations except for pDCs and memory B cells." (PMID 37264110, 2023). "In this regard, highest gene expression by far (83-fold increased expression to controls) displayed the IFN regulatory factor Irf7 during acute CVB3 myocarditis." (PMID 29538462, 2018). "In addition, Omura and colleagues identified the induction of IRF7 as an inflammatory marker of the innate immune system to detect the acute phase of myocarditis and inflammatory cardiomyopathy." (PMID 29538462, 2018). "Consistent with the downregulation of motif activities of IRF3 and IRF7, peripheral immune cells showed a reduced motif activity level of STAT1::STAT2 and IRF9 at the time of myocarditis." (PMID 37264110, 2023).
neuroblastoma (2 papers, 2015 to 2022). Neuroblastoma (NB) is the most common solid, extracranial childhood tumor. "To investigate if IRF7 is critical in soluble amyloid-driven type-1 IFN production in human M17 neuroblastoma cells, we established a stable IRF7 shRNA cell line and treated with 7.5 μM Aβ1-42 for 24 to 72 h." (PMID 25879763, 2015). "Upon stimulation of human neuroblastoma M17 cell cultures with the TLR4 agonist LPS we found that IRF7 knockdown was sufficient to ablate the type-1 IFN response to the bacterial endotoxin." (PMID 25879763, 2015). "A lower correlation was observed between CCL2 level and monocytes/macrophages, and PDC (IRF7) infiltration, suggesting the involvement of CCL2/CCR2 in APC recruitment by neuroblastoma tumors." (PMID 36923280, 2022).
non-small cell lung carcinoma (2 papers, 2023 to 2024). A group of at least three distinct histological types of lung cancer, including non-small cell squamous cell carcinoma, adenocarcinoma, and large cell carcinoma. "IRF7 activated a positive feedback regulatory loop of interferon signaling and subsequently activated the RIG-I-like receptor signaling pathway and BCL-2 expression to inhibit apoptosis and promote proliferation, invasion and migration of non-small cell lung cancer cells." (PMID 37251373, 2023).
pancreatic ductal adenocarcinoma (2 papers, 2022 to 2026). An infiltrating adenocarcinoma that arises from the epithelial cells of the pancreas. "Moreover, immunohistochemical (IHC) validation using tissue microarrays from 20 human pancreatic ductal adenocarcinoma (PDAC) specimens revealed that the overall expression of RASSF1C and hypoxia-inducible factor-1 alpha (HIF-1α) was higher than that of UFL1 and IRF7." (PMID 41912489, 2026).
pancreatitis (2 papers, 2014 to 2021). Inflammation of the pancreas. "In the present study, upregulation of TLR7, IRF7, and IFN-β expression was observed in the pancreatitis-associated DHAV-1 and classical-type DHAV-1 groups, which is consistent with the findings of previous studies." (PMID 34482448, 2021). "However, under conditions of experimental pancreatitis, Ifnar1SA mice exhibited noticeably higher pancreatic tissue levels of IFN-stimulated proteins (STAT1 and PKR) and IFN-stimulated genes such as Irf7 compared with wild type animals." (PMID 24480543, 2014).
pregnancy disorder (2 papers, 2017 to 2024). A disorder that is related to pregnancy. "For the pregnancy disorder upregulated regulons and target genes, we identified that the predicted dNK2/3-associated IRF2 and IRF7 targets were enriched with preeclampsia upregulated genes (IRF2 LOP p = 9.2 × 10–5, 19-fold; IRF7 EOP/LOP (p = 5.0 × 10–5/5.6 × 10–5), 7.1-fold / 8.6-fold)." (PMID 39090334, 2024). "Finally, we also identified five genes (PLCB1, LUM, ADCY7, IRF7, and EHHADH) that we predict to be important for pregnancy disorders and placenta development, although such links remains to be established." (PMID 29222466, 2017).
pulmonary hypertension (2 papers, 2022 to 2023). Increased pressure within the pulmonary circulation due to lung or heart disorder. "MCT-induced pulmonary hypertension was studied in rats and rat PASMCs cells transfected with an adenovirus overexpressing IRF7." (PMID 37251373, 2023).
pyelonephritis (2 papers, 2019 to 2021). An inflammatory process affecting the kidney. "E. coli 83972pap stably reprogrammed host gene expression, by activating an acute pyelonephritis-associated, IRF7-dependent gene network." (PMID 31181116, 2019). "Small RNA-based inhibition of the IRF-7 transcription factor was effective in a murine pyelonephritis model, and IL-1RA therapy prevented severe cystitis and accelerated bacterial clearance in an acute cystitis model." (PMID 34467240, 2021). "This is explained mechanistically by bacterial reprogramming of host gene expression, including the activation of IRF-7; a transcription factor that defines tissue pathology in the murine pyelonephritis model." (PMID 31181116, 2019).
renal cell carcinoma (2 papers, 2024 to 2025). "For instance, circ-AKT3 regulates miR-296-3p/E-cadherin signaling in diabetic nephropathy, while circ-EGLN3 influences miR-1299/IRF7 in renal cell carcinoma (RCC)." (PMID 41194001, 2025).
Rotavirus infection (2 papers, 2019 to 2022). Infection with any of the rotaviruses. "Mechanically, we confirmed that the silence of the eIF4F complex suppressed the protein level of IRF1 and IRF7 that exert potent antiviral effects against rotavirus infection." (PMID 30934842, 2019). "This suggests that other pathways (e.g. m6A modifications in RV RNA), besides that mediated by Irf7, may also play roles in the rotavirus-infection-resistant phenotype of IECs from Mettl3ΔIEC mice." (PMID 35098923, 2022). "Thus, in this study, we have dissected the effects of the cellular translation machinery, the eIF4F complex, on rotavirus infection, and we found that the eIF4F complex is an essential host factor in counteracting rotavirus infection through regulating the antiviral protein IRF1 and IRF7." (PMID 30934842, 2019).
Salmonella Infections (2 papers, 2019 to 2025). Infections with bacteria of the genus SALMONELLA. "SLAMF7 and SLAMF8 signal through NF-κB, IRF7, and STAT-1, and limit mitochondrial ROS accumulation upon Salmonella infection." (PMID 40231463, 2025).
triple-negative breast carcinoma (2 papers, 2021 to 2022). An invasive breast carcinoma which is negative for expression of estrogen receptor (ER), progesterone receptor (PR), and human epidermal growth factor receptor 2 (HER2). "Also, another study showed that basic transcription factor 3 (BTF3), a transcription initiation factor in RNA pol II promoted the stemness and suppressed the interferon regulatory factor 7 (IRF7) in triple-negative breast cancer." (PMID 36550571, 2022).
uveitis (2 papers, 2016 to 2024). An inflammatory process affecting a part of or the entire uvea. "We carried out a two-stage case control study to investigate the association of 13 SNPs of TRIM20, IRF3, IRF7, IRF8, MYD88 and NF-κB1 in two different uveitis entities." (PMID 26794091, 2016).
viral myocarditis (2 papers, 2018 to 2021). Myocarditis that is caused by an infection with a viral agent. "Our results underline the potential disease-phase dependent role of IRF7 to robust IFN induction in acute viral myocarditis." (PMID 29538462, 2018). "Ultimately, IRF7 is released, which causes viral myocarditis." (PMID 34970593, 2021). "Importantly, Irf7 is a transcription factor responsible for the amplification of the IFN response in viral myocarditis." (PMID 29538462, 2018).
acute lung injury (1 paper, 2020). A condition of lung damage that is characterized by bilateral pulmonary infiltrates (pulmonary edema) rich in neutrophils, and in the absence of clinical heart failure. "The excessive activation of IRF7 promotes the development of acute lung injury (ALI) caused by influenza A virus (IAV), and attenuating IRF7 activity can significantly prevent the progression of IAV-induced ALI in model mice." (PMID 32969837, 2020).
Aicardi-Goutières syndrome (1 paper, 2021). "We next examined baseline gene expression (qPCR) of archetypal interferon stimulated genes (ISGs) IFI27, USP18, MX1, OASL, IRF7, and MX2, and those ISGs found highly expressed in PBMCs from the type 1 interferonopathy, Aicardi-Goutières syndrome (AGS) patients (IFI27, ISG15, IFI44L, and RSAD2)." (PMID 33746960, 2021).
airway allergy (1 paper, 2019). "Interestingly, Irf7−/− and Ifnar2−/− (deficient for type I IFN receptor) mice displayed normal dendritic cell development and allergic airway sensitization in response to HDM81, suggesting independence between type I IFN signaling and HDM-induced airway allergy when Tet1 is present." (PMID 31089182, 2019).
alopecia (1 paper, 2022). Hair loss usually from the scalp. "The expression level of IRF7 was negatively associated with the incidence of alopecia." (PMID 35757684, 2022).
Anxiety (1 paper, 2020). Intense feelings of nervousness, tension, or panic often arise in response to interpersonal stresses. "Although wildtype mice develop no disease signs, they showed reduced anxiety-like behavior and impaired memory formation, whereas Irf-7−/− mice were not affected." (PMID 32951602, 2020).
avian influenza (1 paper, 2025). Infection of domestic and wild fowl and other birds with influenza A virus. "Overexpression of IRF7 has been observed in chickens challenged with avian influenza, indicating its capacity to regulate various cellular processes within the host’s innate immune response." (PMID 41042757, 2025).
B cell lymphoma (1 paper, 2025). "STAT3 inhibition also synergized with inducers of type I IFN, a downstream effector of the cGAS-STING pathway, to effectively inhibit B cell lymphoma growth, possibly by alleviating the suppressive effects of STAT3 on IRF7, IRF9, STAT1, and STAT2 expression." (PMID 40743845, 2025).
breast tumor (1 paper, 2026). "However, analysis of scRNAseq breast tumor data showed strong positive correlations between BRRIAR and RIG-I (Spearman’s r = 0.65, p = 2.4e-15) or IRF7 (Spearman’s r = 0.64, p = 2.2e-16), suggesting elevated RIG-I signaling in BRRIAR-positive cells." (PMID 41501810, 2026).
Chlamydia infection (1 paper, 2015). "Our data show that the transcription factor IRF7 was induced late during Chlamydia infection, which is indicative of a positive feedback mechanism of IFN-β synthesis late during infection." (PMID 25798928, 2015). "In contrast, IRF7 appears to play little or no role in the early synthesis of IFN-β during Chlamydia infection." (PMID 25798928, 2015). "Our data proposes that the initial wave of IFN-β synthesized early during Chlamydia infection is TLR3-dependent and occurs through pathways involving IRF3; while late stage IFN-β synthesis is triggered by the type-1 IFN secreted into the supernatants, and signals through pathways that require IRF7." (PMID 25798928, 2015).